CD163 (CD163 molecule)
Diseases named in the same sentence as CD163 in open-access papers (continued):
Sharing a sentence is not in itself a finding about the gene and the disease.
schizophrenia (continued). "In our study, transcript levels of CD16, a marker of natural killer cells and activated macrophages/monocytes, CD163 a marker of perivascular macrophages and CD14, a marker of monocytes were all elevated in schizophrenia cases with high inflammation." (PMID 30214039, 2020). "We sought to distinguish between macrophages and resident microglia in the brain parenchyma with double-label fluorescence immunohistochemistry for CD163 and the pan-microglial marker IBA1 in the high inflammatory/schizophrenia cases." (PMID 33133060, 2020). "Finally, macrophage recruitment chemokine CCL2 mRNA was increased in schizophrenia (>200%, p < 0.0001) and CCL2 mRNA levels positively correlated with CD163 mRNA (r = 0.46, p < 0.0001)." (PMID 35844224, 2022). "CD163 and intercellular adhesion molecule 1 (ICAM1), which is responsible for peripheral immune cell recruitment, both have increased mRNA expression in the prefrontal cortex of the high inflammation subgroup in schizophrenia." (PMID 34911938, 2021). "We found CD163+ cells around blood vessels and in the parenchyma and increases in ICAM1, CD163, CD64, and FN1 mRNAs as well as increases in all complement transcripts in the midbrain of schizophrenia cases with high inflammation." (PMID 33133060, 2020). "Evidence suggests that macrophages may enter the brain in schizophrenia, as increases in the vascular macrophage capture molecule, intercellular cell adhesion molecule 1 (ICAM1) and increases in CD163 mRNAs are found in the cortex and hippocampus." (PMID 33133060, 2020). "Here, we hypothesized that markers consistent with infiltrating macrophages (ICAM1, CD163, and FN1 mRNAs) would be increased in midbrain parenchyma near dopamine cell bodies in people with schizophrenia and a high inflammatory biotype." (PMID 33133060, 2020). "CD163 mRNA was strongly positively correlated with CD59 mRNA in schizophrenia cases (r = 0.52, p = 0.007) but not in controls (r = −0.008, p = 0.97) and the z transformation test was significantly different (z = −2.05, p = 0.04)." (PMID 33133060, 2020). "We further predicted that one of the macrophage markers, CD163 mRNA, would correlate with the “M1-like” marker CD64, and that these increases in pro-inflammatory macrophage markers may be specific to high inflammation schizophrenia subgroup." (PMID 35844224, 2022). "The changes in endothelial genes and increased density of CD163+ macrophage may suggest that more macrophages are infiltrating the brain specifically in high inflammation schizophrenia subgroup, but it is not known if this would also occur in normal controls defined as having high inflammation." (PMID 35844224, 2022). "A higher density of CD163+ macrophages was reported in the subependymal zone of patients with schizophrenia, suggesting increased ingression of immune cells into the brain parenchyma and supporting the hypothesis of a less stringent BBB function in schizophrenia." (PMID 36192459, 2022).
colitis (13 papers, 2017 to 2025). Inflammation of the colon. "In fact, we show that i/niColAMs dynamically reflect shifts in macrophage function that track with colitis severity—something conventional markers (like CD163) fail to do." (PMID 40766554, 2025). "In fact, we show that iColAMs and niColAMs dynamically reflect shifts in macrophage function that track with colitis severity—something conventional markers (e.g., CD163) fail to do." (PMID 41321314, 2025). "The results demonstrated that HIF-MSC injection promoted a decrease in the relative expression ratio of F4/80+CD86+ and an increase in that relative expression ratio of F4/80+CD163+ in the colonic tissues of experimental colitis mice (p < 0.05)." (PMID 36979804, 2023). "Treating the colitis mice with the ginsenoside Rg1 and Rock1 inhibitor Y27632 upregulated the peripheral blood CD11b+F4/80+CD163+ M2 macrophages." (PMID 36072401, 2022). "Immunofluorescence examination of sigmoid colonic tissues demonstrated that DSS-induced colitis significantly upregulated pro-inflammatory macrophage markers (CD68, CD86) while downregulating the anti-inflammatory marker CD163 relative to NC." (PMID 40725052, 2025). "In this study, the percentage of M1 macrophage CD11b+F4/80+iNOS+ was significantly increased in DSS-induced colitis mice, and those of M2 macrophage CD11b+F4/80+CD206+ and CD11b+F4/80+CD163+ cells were significantly downregulated." (PMID 34567209, 2021). "After administration of Cur, the percentage of CD11b+F4/80+iNOS+ macrophages in colitis mice was significantly downregulated, and those of M2 macrophage CD11b+F4/80+CD206+ and CD11b+F4/80+CD163+ macrophages were significantly upregulated." (PMID 34567209, 2021). "Importantly, macrophage activation was suppressed and M1/M2 macrophage polarization was regulated in colitis mice, and the percentage of CD11b+F4/80+ and CD11b+F4/80+TIM-1+ and CD11b+F4/80+iNOS+ decreased significantly and CD11b+F4/80+CD206+ and CD11b+F4/80+CD163+ increased significantly." (PMID 34567209, 2021). "The scavenger receptors CD163 and CD206 as well as the anti-inflammatory cytokine IL-10 were selectively induced in GRflox but not GRlysM mice during DSS-induced colitis." (PMID 29324769, 2018). "In response to PNU-282987 treatment, we detected a significantly decreased number of CD68+M1 macrophages compared with the colitis model group, while the number of CD68+CD163+ M2 macrophages did not change, and the overall ratio of M1/M2 macrophages decreased significantly." (PMID 36058917, 2022).
periodontitis (13 papers, 2016 to 2025). An acute or chronic inflammatory process that affects the tissues that surround and support the teeth. "In the case of periodontitis, which is associated with the dominant type of M1 macrophage, the application of MSCs reduces the expression of the original macrophage-associated CD163 in tissues, which is unfavorable for tissue repair." (PMID 30140291, 2018). "Between-group comparisons revealed lower CD163 levels (p = 0.004) and a higher CD80/CD163 ratio (p = 0.002) in the periodontitis group than in the periodontally healthy group." (PMID 36286036, 2022). "The decreased levels of CD163 in our study were more prominent in periodontitis lesions than in peri-implantitis lesions." (PMID 36286036, 2022). "CD163 + CD206+ cells are less frequently detected in periodontitis lesions than in healthy tissue samples, which is in line with this finding." (PMID 36286036, 2022). "Our results indicate that the anti-inflammatory, pro-repair nature of CD163 is restrained in tissues affected by periodontitis, which possibly contributes to the disproportionate inflammatory response." (PMID 36286036, 2022). "An increased CD80/CD163 or CD80/CD206 ratio was also expected from peri-implantitis lesions when compared to periodontitis, due to prior research demonstrating that M1 polarization occurs more prominently in peri-implantitis lesions." (PMID 36286036, 2022). "CD163 was found to hold PD diagnostic capabilities, as levels significantly increased from healthy tissue to disease, tagging CD163 as a promising periodontitis biomarker." (PMID 35453967, 2022). "We found the CD80/CD206 ratio to be similar across groups, while a disrupted CD80/CD163 balance was observed in patients with periodontitis, possibly corresponding to the increasing pro- to anti-inflammatory macrophage ratios." (PMID 36286036, 2022). "The more pronounced elevation of the CD80/CD163 ratio and decrease of CD163 levels in periodontitis lesions indicate different immune characteristics in periodontal and peri-implant lesions." (PMID 36286036, 2022). "Within the limitations of this study, the CD80/CD163 balance seems to be disrupted in periodontitis and peri-implantitis." (PMID 36286036, 2022). "The present study demonstrates an increased CD80/CD163 ratio and decreased CD163 protein levels in tissues affected by periodontitis when compared to healthy gingiva." (PMID 36286036, 2022). "A disruption in CD80/CD163 balance seems to be related to the pathogenesis of periodontitis and peri-implantitis, being less prominent in the latter." (PMID 36286036, 2022). "To confirm the presence of macrophages, we also examined the expression of the macrophage markers CD14, CD68, CD86, and CD163 in gingival biopsies from periodontally healthy individuals and periodontitis patients." (PMID 33513808, 2021). "The presence of macrophage markers CD14, CD86, CD68, and CD163 was examined in gingival biopsies from healthy individuals and periodontitis patients." (PMID 33513808, 2021). "The macrophage is the cell responsible for the release of CD163 and is an important immune cell in the pathogenesis of periodontitis." (PMID 32656036, 2020). "Comparing Oral Leukoplakia and Oral Lichen with Periodontitis, both potentially malignant transforming lesions showed significantly (p=0.029) increased IL-23R cell densities and Labeling Indices as well as a significantly increased CD163/CD11c ratio (p=0.029)." (PMID 40297579, 2025). "No statistical difference was observed in CD163 levels and CD80/CD163 ratio between the periodontitis and peri-implantitis groups (p = 0.402, p = 0.270, respectively) or between the periodontal health and peri-implant health groups (p = 0.594, p = 0.859, respectively)." (PMID 36286036, 2022). "However given that CD163, an M2 macrophage marker, may also be a biomarker of healthy gingival tissue the role of M2 macrophages in the progression of chronic periodontitis remains unclear." (PMID 27383471, 2016).
periodontitis (continued). "Subsequently, we investigated macrophage polarization and noted a significant decrease in M2 macrophages (CD68+CD163+) and an increase in M1 macrophages (CD68+CD86+) in periodontitis samples." (PMID 40277454, 2025). "CD163 levels were found to be decreased (p = 0.004), and the CD80/CD163 ratio was found to be elevated (p = 0.002) in periodontitis lesions compared to healthy gingiva." (PMID 36286036, 2022). "It would appear that either CD163 mRNA is not translated to the protein form or the translated protein is degraded rapidly due to the high proteolytic activity in tissues affected by periodontitis." (PMID 36286036, 2022). "Finally, a thorough description of CD80, CD163, and CD206 levels, and their ratios in the oral fluids of periodontitis and peri-implantitis patients, may allow them to be considered as early markers of these diseases." (PMID 36286036, 2022). "Therefore, the aim of this study was to compare CD80, CD163, and CD206 levels and their ratios in soft tissue samples of periodontitis, peri-implantitis, clinically healthy gingiva, and clinically healthy peri-implant mucosa, irrespective of the number of cells expressing them." (PMID 36286036, 2022). "According to our results, the reduced tissue levels of CD163 but not of CD206 are related to periodontitis, which might be on account of their distinct characteristics." (PMID 36286036, 2022).
squamous cell carcinoma (13 papers, 2020 to 2025). A carcinoma arising from squamous epithelial cells. "Generally, patients with more TAM infiltration around tumor cells have a poorer prognosis, and CD163+ macrophage infiltration is associated with a poor prognosis in squamous cell carcinoma." (PMID 38893259, 2024). "It was recently shown that tongue CD163+ macrophages infiltrate tumor tissue in squamous cell carcinoma at a high frequency." (PMID 35749158, 2022). "During radiotherapy, the proportions of MDSCs were clearly increased in adenocarcinoma patients and the percentages of CD68+CD163+M2-like macrophages were markedly elevated in squamous carcinoma patients." (PMID 35928634, 2022). "Higher densities of CD68+ and CD163+ cells were also observed in HPV+ tumors of other HPV-induced squamous cell carcinomas, such as oropharyngeal squamous cell carcinoma and cervical squamous cell carcinoma." (PMID 34194435, 2021). "The results revealed that Spi-B expression was positively associated with CD163 expression in adenocarcinoma (ADC) and squamous cell carcinoma (SCC)." (PMID 34141615, 2021). "In parallel, CD163—a marker of M2 macrophages involved in immunosuppression and tissue remodeling —was detected in all three tissue types, with a moderate increase in squamous carcinoma (++), indicating a progressive activation of the stromal immune response." (PMID 41155492, 2025). "There were also moderate correlations between CD163 and VEGF-A (Pearson correlation r = 0.356, p < 0.001) or VEGF-C (Pearson correlation r = 0.325, p < 0.001) expression in squamous cell carcinoma." (PMID 33228719, 2020).
steatosis (13 papers, 2015 to 2024). Increased lipid within the cytoplasm of cells. "In conclusion, our study demonstrated association between hepatic expression of IL-4, IL-17, and CD163 with severity of HCV, being more expressed in moderate and marked grades of activity, late stages of fibrosis, and higher degrees of steatosis." (PMID 33906302, 2021). "Current study revealed increased expression of CD163 in high inflammatory grades, high fibrotic stages, and marked degree of steatosis of chronic HCV." (PMID 33906302, 2021). "Patients with low-grade steatosis were found to have higher mRNA expression of M2 markers, CD206 and CD163, compared to patients with advanced steatosis." (PMID 30555477, 2018). "This is also in accordance with the present data showing that the main effect of the CD163-directed therapy was on the secondary liver changes, whereas less reduction of the direct fructose-induced hepatocyte changes such as steatosis was seen." (PMID 28344991, 2017). "The present rat data show a strong positive effect of specific dexamethasone targeting to the M2 macrophage receptor CD163 in an inflammatory model, where fructose induces rapidly progressing steatosis followed by inflammation, hepatocyte ballooning, and fibrosis mimicking human NASH." (PMID 28344991, 2017). "Interestingly, several proteins associated with steatosis and fibrosis were significantly correlated with markers of cholesterol metabolism (VLDL, HDL, triglycerides), inflammation (CD14, CD163, IL6), as well as cardiometabolic diseases, HIV-specific parameters, and ART, but not with SNPs." (PMID 39426127, 2024).
hemorrhage (12 papers, 2013 to 2025). Loss of blood from the vascular compartment to the exterior or into nonvascular body space as a result of rupture or severance of the blood vessels. "Our work thus demonstrates that 64Cu-DOTATATE PET can be used to detect a hemorrhage-associated subpopulation of macrophages (CD163+) in vivo in atherosclerotic plaques of the internal carotid arteries." (PMID 25977567, 2015). "While CD163 expression in human neurons after intracranial haemorrhage is unclear, this has been demonstrated in animal models." (PMID 40763130, 2025). "The role of CD163 (including sCD163) in hemoglobin clearance in hemorrhage has been extended in other tissues, such as in hepatic hemorrhage." (PMID 39451197, 2024). "CD163 mRNA expression displayed a weak increasing trend to macrophages, and moderate increasing trends to lipids and intraplaque hemorrhage, as well as to MMP-1 and MMP-9." (PMID 32873809, 2020). "In a mouse model of intracerebral haemorrhage, CD163 appeared to be detrimental in the first 4 days after the bleed but then conferred protection after 4 days." (PMID 32346673, 2020). "In summary, brain CD163 levels were increased in the acute phase of SAH, which was associated with hemorrhage severity, T2 lesion on MRI and hydrocephalus after SAH." (PMID 29867324, 2018). "Our finding substantiate that 64Cu-DOTATATE is correlated primarily with CD163 positive macrophages (CD163+) and only weaker with CD68 positive macrophages (CD68+) making 64Cu-DOTATATE uptake a predictor of (hemorrhage-associated macrophages) macrophage activity." (PMID 25977567, 2015).
leukoplakia (12 papers, 2015 to 2025). A white patch or plaque on a mucous membrane that cannot be characterized clinically or pathologically as any other disease. "In addition, an increase in macrophage infiltration and a shift towards CD163-positive, M2-polarized macrophages in oral leukoplakia were associated with malignant transformation during a 5-year follow-up." (PMID 35406584, 2022). "Comparing Oral Lichen Planus and Oral Leukoplakia, CD163 cell density (mean 514 cells/mm2 vs. 50 cells/mm2, p=0.029) and CD163/CD68 expression ratio (2.26 vs. 0.51, p=0.029) were significantly higher in Lichen lesions." (PMID 40297579, 2025). "Immunohistochemical staining of CD68, CD80, and CD163 on the normal oral mucosa and oral leukoplakia revealed that the three macrophage markers were rarely found in the normal oral mucosa." (PMID 36105288, 2022). "To further characterize the CD163+ macrophages in leukoplakia, we examined the coexpression of CD163 and STAT1 or pSTAT1 using double-labeling immunofluorescence." (PMID 26242181, 2015). "The results demonstrated that although CD163 has been considered a M2 macrophage marker in many solid tumors, the CD163+ macrophages in oral leukoplakia appear to possess an M1 phenotype characterized by the expression of IFN-inducible gene products." (PMID 26242181, 2015). "Using CD68 (pan-MΦ), CD80 (M1 MΦ), CD163 (M2 MΦ), and a simple binary model of macrophage phenotype (M1-CD80 versus M2-CD163), they could only observe a significant increase in CD163+ cells in dysplastic leukoplakias, while CD68 and CD80 remained the same." (PMID 37190121, 2023). "However, the authors claim that CD163+ macrophages are actually more like M1 macrophages in the context of the progression of leukoplakias towards cancer." (PMID 37190121, 2023). "Immunohistochemical analysis of resected oral leukoplakia specimens showed that, compared with patients that exhibited low CD163+ macrophage amounts, leukoplakia lesions exhibited a high amount of CD163+ macrophages, which was usually accompanied by abnormal Ki-67 expression and keratin loss." (PMID 36105288, 2022). "Oral leukoplakia was associated with significantly higher PD-L1 expression and increased numbers of subepithelial CD163+ cells in the non-smoking group compared with the smoking group." (PMID 33861793, 2021). "In addition, the CD163/CD11c ratio in Oral Leukoplakia was significantly (p=0.016) increased." (PMID 40297579, 2025). "Macrophage infiltration is rare in normal oral mucosa epithelium, but is increased in OPMD like oral leukoplakia, and the immunosuppressive M2 phenotype macrophage infiltration (especially CD163+, but not CD204+ or CD206+) is associated with the deterioration of the disease." (PMID 39068492, 2024). "The abundance of CD68 and CD163 in OSCC were significantly higher than those in normal oral mucosa and oral leukoplakia." (PMID 36105288, 2022). "We examined the infiltration of macrophages for various pathological grades of leukoplakia using antibodies to CD68, CD80, and CD163." (PMID 26242181, 2015). "In the present study, we evaluated the relationship between infiltrated T cells and the polarization of TAMs in oral leukoplakia and found a positive correlation between the numbers of CD4+ T cells and CD163+ macrophages." (PMID 26242181, 2015). "Whereas, the abundance of CD163 in tissues with moderate leukoplakia was significantly higher compared to those without dysplasia." (PMID 36105288, 2022). "Finally, we found that the myeloid cells subgroup in the HNSCC group highly expressed the marker genes of M2 macrophages such as CD163 and CD209, indicating that the tumor promoting effect of myeloid cells in the HNSCC group was stronger than that of leukoplakia." (PMID 38582791, 2024).
leukoplakia (continued). "We examined differences in programmed death-ligand 1 (PD-L1) expression and subepithelial CD163+ TAM and CD8+ cell/lymphocyte counts in the microenvironment of oral leukoplakia of smoking and non-smoking patients and investigated their associations with malignant transformation." (PMID 33861793, 2021).